MGAT5 (alpha-1,6-mannosylglycoprotein 6-beta-N-acetylglucosaminyltransferase)
Description:
Catalyzes the addition of N-acetylglucosamine (GlcNAc) in beta 1-6 linkage to the alpha-linked mannose of biantennary N-linked oligosaccharides. Catalyzes an important step in the biosynthesis of branched, complex-type N-glycans, such as those found on EGFR, TGFR (TGF-beta receptor) and CDH2. Via its role in the biosynthesis of complex N-glycans, plays an important role in the activation of cellular signaling pathways, reorganization of the actin cytoskeleton, cell-cell adhesion and cell migration. MGAT5-dependent EGFR N-glycosylation enhances the interaction between EGFR and LGALS3 and thereby prevents rapid EGFR endocytosis and prolongs EGFR signaling. Required for efficient interaction between TGFB1 and its receptor. Enhances activation of intracellular signaling pathways by several types of growth factors, including FGF2, PDGF, IGF, TGFB1 and EGF. MGAT5-dependent CDH2 N-glycosylation inhibits CDH2-mediated homotypic cell-cell adhesion and contributes to the regulation of downstream signaling pathways. Promotes cell migration. Contributes to the regulation of the inflammatory response. MGAT5-dependent TCR N-glycosylation enhances the interaction between TCR and LGALS3, limits agonist-induced TCR clustering, and thereby dampens TCR-mediated responses to antigens. Required for normal leukocyte evasation and accumulation at sites of inflammation (By similarity). Inhibits attachment of monocytes to the vascular endothelium and subsequent monocyte diapedesis. [Secreted alpha-1,6-mannosylglycoprotein 6-beta-N-acetylglucosaminyltransferase A]: Promotes proliferation of umbilical vein endothelial cells and angiogenesis, at least in part by promoting the release of the growth factor FGF2 from the extracellular matrix.
Synonyms: GNT-V; MGAT5A; GNT-VA; glcNAc-T V
Tractability: Small molecule: a structure with a bound ligand is known. Antibody: UniProt places it where antibodies can reach, with high confidence; UniProt predicts a signal peptide or a membrane-spanning region; its Gene Ontology location is reachable by antibodies, with medium confidence. PROTAC: ubiquitination databases record sites on it; its protein half-life has been measured.
Target class: Enzyme; Transferase
Gene: Protein-coding gene on chromosome 2 (134,119,933 to 134,454,621, forward strand). Ensembl gene ENSG00000152127.
Subcellular location: Golgi apparatus membrane; Secreted (Secreted alpha-1,6-mannosylglycoprotein 6-beta- N-acetylglucosaminyltransferase A)
Pathways (Reactome):
Disease: Maturation of spike protein
Metabolism of proteins: N-Glycan antennae elongation
Gene Ontology:
Molecular function: alpha-1,6-mannosylglycoprotein 6-beta-N-acetylglucosaminyltransferase activity; manganese ion binding; protein phosphatase inhibitor activity; acetylglucosaminyltransferase activity; glycosyltransferase activity
Biological process: positive regulation of cell migration; positive regulation of receptor signaling pathway via STAT; protein N-linked glycosylation; viral protein processing; glycoprotein biosynthetic process
Cellular component: extracellular exosome; extracellular region; membrane; Golgi apparatus; Golgi membrane
Genetic constraint (gnomAD): Loss-of-function variants: 26 observed, 87 expected, observed/expected ratio (o/e) 0.3, 90% interval 0.22 to 0.41. The upper end of that interval is the gene's LOEUF score, 0.41, which puts it in group 1 of 6, group 1 being the genes least tolerant of losing a copy. Missense variants: 638 observed, 899.77 expected, observed/expected ratio (o/e) 0.71, 90% interval 0.66 to 0.76. Synonymous variants: 292 observed, 327.06 expected, observed/expected ratio (o/e) 0.89, 90% interval 0.81 to 0.98.
Homologues: Orthologues: chimpanzee MGAT5 (100% identical), macaque MGAT5 (99% identical), rabbit MGAT5 (98% identical), pig MGAT5 (98% identical), mouse Mgat5 (97% identical), guinea pig MGAT5 (96% identical), rat Mgat5 (95% identical), dog MGAT5 (93% identical), Caenorhabditis elegans gly-2 (31% identical). Paralogues in human: MGAT5B (45% identical), CCDC126 (5% identical).
Diseases named in the same sentence as MGAT5 in open-access papers:
MGAT5 is named in the same sentence as 92 diseases in open-access papers, as found by Europe PMC text mining. Sharing a sentence is not in itself a finding about the gene and the disease. The quoted sentences say what the papers report.
breast cancer (28 papers, 2007 to 2025). A primary or metastatic malignant neoplasm involving the breast. "Loss of Mgat5 in breast cancer led to a decrease in tumor growth and an increase in the production of IFN-γ and TNF-α in splenocytes." (PMID 38912584, 2024). "More recently, miR-124-3p was reported to be downregulated in breast cancer cells, where it inhibited cell proliferation and metastasis by targeting N-acetylglucosaminyltransferase V (MGAT5), a tumorigenesis and metastasis-associated enzyme in breast cancer." (PMID 33435254, 2021). "Inhibition of cancer-associated MGAT5 is considered a potential therapeutic target, and has led to immune activation in a breast cancer mouse model." (PMID 32849657, 2020). "Among these, only ETS1 showed a strong negative correlation with ACVR1B and a positive correlation with MGAT5 in TCGA pancreatic and breast cancer cohorts, implicating ETS1 in ALK4 loss-mediated MGAT5 upregulation." (PMID 41408046, 2025). "miR-124-3p achieves this inhibition by targeting N-acetylglucosaminyltransferase V (MGAT5), a correlation which has been shown in in vitro and in vivo breast cancer mouse models." (PMID 36613642, 2022). "In present study, we validated the increased MGAT5 protein and its glycosylation products in breast cancer." (PMID 36185271, 2022). "The expressions of a glycogene MGAT5 as well as its products were validated by immunohistochemistry and western blotting in breast cancer tissues and cells." (PMID 36185271, 2022). "The findings of the IHC staining revealed that the MGAT5 protein was high expressed in breast cancer cells." (PMID 36185271, 2022). "Our results revealed that PHA-L labeled signal was higher in breast cancer tissues, which indicated increased glycan products modified by MGAT5." (PMID 36185271, 2022). "The validation of MGAT5 protein suggests a probable pathway and target for the development and treatment of breast cancer." (PMID 36185271, 2022). "Studies have found that BRIP1 can promote the invasion of breast cancer (BC) cells by regulating the expression of multiple downstream target genes, such as MGAT5, EPCAM, and CXCL12, especially in the triple-negative phenotype MDA-MB-231 cell line." (PMID 34408776, 2021). "GnT-V (Mgat5)-null mice appeared normal but exhibited reduced tumor growth and progression in a PyMT-induced mammary tumor model, showing that the β1,6-branch plays key roles in tumor progression in vivo." (PMID 27136596, 2016). "MGAT5, responsible for adding β1,6-GlcNAc branches to N-glycans, can promote immune evasion and oncogenic signaling in multiple solid tumors, including pancreatic, ovarian, and breast cancers." (PMID 41061966, 2025). "MGAT5 expression was also increased in breast cancer tissues." (PMID 36185271, 2022). "Abnormal glycosylation of key protein by MGAT5 may explain the mechanism of breast cancer development." (PMID 36185271, 2022). "Downstream glycosylation products of MGAT5 were all increased in breast cancer." (PMID 36185271, 2022). "MGAT5, which synthesized the branching GlcNAc structures, was chosen for preliminary verification because it is an important glycosyltransferase that is overexpressed in breast cancer." (PMID 36185271, 2022). "For example, mammary tumor growth and metastasis induced by the polyomavirus middle T (PyMT) oncogene are reduced in Mgat5−/− mice (knockout for the gene encoding MGAT5), whereas Mgat3−/− mice (knockout for the gene encoding MGAT3) exhibit an accelerated appearance of mammary tumors induced by PyMT." (PMID 26539643, 2016). "Potential oncogenes amplified in the breast cancer include GREB1, NRXN1, MGAT5, PKP4, DAPL1, ITGB6, and RBMS1, which may be implicated in carcinogenesis, proliferation, and invasion." (PMID 26432421, 2015). "Besides, we tested the levels of MGAT5 glycan products in breast cancer tissues." (PMID 36185271, 2022). "Additionally, highly expressed MGAT5 was validated in breast cancer tissues and cells." (PMID 36185271, 2022).
breast cancer (continued). "Interestingly, mice with mammary tumours induced by the polyomavirus middle T (PyMT) oncogene (whose expression promotes increased PI3K/AKT1and RAS/MEK/ERK signaling) showed a decrease in tumour growth in Mgat5−/− mice." (PMID 28880250, 2017). "In breast cancer, MGAT1, MGAT2 and MGAT3 were downregulated, but MGAT4A, MGAT4B, and MGAT5 were increased." (PMID 36185271, 2022). "Consistently, in the early-stages of these PyMT Mgat5−/− mammary tumours they also show lower levels of activation of the PI3K/AKT1signaling, and the cell lines derived from the PyMT Mgat5−/− are less responsive to insulin-like growth factor (IGF)." (PMID 28880250, 2017). "In agreement with the phenomenon observed in sarcoma cells, Pierce and colleagues showed that knocking down of MGAT5 expression, which led to decreased synthesis of galectin-3 ligands in molecules such as the EGFR, interfered with the migratory response of breast cancer cells in response to EGF." (PMID 22216245, 2011).
gastric cancer (14 papers, 2007 to 2024). A primary or metastatic malignant neoplasm involving the stomach. "Hydrogen sulfide was shown to cause anti-gastric cancer effects through targeting MGAT5, highlighting its potential as a therapeutic target." (PMID 37256183, 2023). "The published study has also reported that inhibition of MGAT5 activity impairs the growth and metastasis of gastric cancer." (PMID 37427332, 2023). "Analysis of the gastric cancer samples from the database revealed a significant positive correlation between MGAT5, MMP13, and RUNX2 expression." (PMID 37256183, 2023). "Inhibition of MGAT5 activity can suppress the growth and metastasis of gastric cancer and inhibit cell invasion and proliferation in glioblastoma." (PMID 37427332, 2023). "In this study, we only discussed the regulatory effect of ISLR and MGAT5 on the progression of gastric cancer cells." (PMID 37427332, 2023). "MGAT5, MMP13, and RUNX2 were significantly positively associated with each other in gastric cancer based on the GEPIA database." (PMID 37256183, 2023). "In gastric cancer cells, the overexpression of MGAT5 leads to a severe peritoneal dissemination of tumor cells in athymic mice, which was attributed to the prolonged stabilization of matriptase." (PMID 26539643, 2016). "Integrin α3β1-mediated cell migration on the laminin 5 substrate is greatly enhanced after the overexpression of MGAT5 in gastric cancer cells." (PMID 26539643, 2016). "Moreover, upregulated RUNX2 in gastric cancer also promotes gastric cancer progression through transcriptional activation of MGAT5 and MMP13." (PMID 38430423, 2024). "Hydrogen sulfide inhibits MGAT5 and displays antitumor efficacy in gastric cancer MMP13 has been shown to be upregulated in gastric cancer and can be inhibited by SIRT1 which modulates the STAT3/MMP13 axis to suppress cell proliferation and metastasis in gastric cancer." (PMID 37256183, 2023). "ISLR interacted with MGAT5 to promote the malignant progression of gastric cancer." (PMID 37427332, 2023). "Accordingly, overexpression of MGAT5-mediated branched N-glycans both in gastric cancer cells and transgenic mice models led to a significant decrease of O-mannosyl glycans attached to E-cadherin that was associated with impairment of its tumour suppressive functions." (PMID 27533452, 2016). "The present study aimed to investigate the role of the immunoglobulin superfamily containing leucine-rich repeat (ISLR) gene in gastric cancer and examine whether ISLR could interact with N-acetylglucosaminyltransferase V (MGAT5) to affect the malignant progression of gastric cancer." (PMID 37427332, 2023). "MGAT5 overexpression weakened the effects of ISLR knockdown on suppressing the viability, proliferation, migration, invasion, and EMT of gastric cancer cells." (PMID 37427332, 2023). "This study is the first to demonstrate the suppressive role of ZBTB16 silencing in gastric cancer and present a novel regulatory relationship between ISLR and MGAT5 in gastric cancer." (PMID 37427332, 2023). "This highlights RUNX2, MGAT5 and MMP13 as key biomarkers of metastatic gastric cancer and therapeutic targets for much-needed anti-gastric cancer drugs." (PMID 37256183, 2023). "In this study, it was uncovered that RUNX2 activates the transcription of MGAT5 and MMP13 which act to facilitate gastric cancer metastasis in vitro and in vivo." (PMID 37256183, 2023). "In summary, we identify MGAT5 and MMP13 as novel RUNX2 targets with known metastatic potential in gastric cancer cells and tissue." (PMID 37256183, 2023). "Consistent with previous studies, we observed high RUNX2 expression in gastric cancer cells which promoted MMP13 and MGAT5 expression." (PMID 37256183, 2023). "Together, these data revealed a role for RUNX2 in independently regulating the expression of MGAT5 and MMP13, the RUNX2/MGAT5/MMP13 positive axis in gastric cancer." (PMID 37256183, 2023).
gastric cancer (continued). "Collectively, these data reveal that RUNX2 enhances MGAT5 and MMP13 expression in gastric cancer cells and represents a biomarker and potential therapeutic target for gastric cancer therapy." (PMID 37256183, 2023). "Taken together, the expression of ISLR and MGAT5 was increased in gastric cancer cells and interference with ISLR inhibited the proliferation, invasion, migration, and EMT of gastric cancer cells, which could be reversed by MGAT5 overexpression." (PMID 37427332, 2023). "The expression of ISLR and MGAT5 in human normal gastric epithelial cells and human gastric cancer cells, and the transfection efficiency of ISLR interference plasmids and MGAT5 overexpression plasmids were all detected by reverse transcription-quantitative PCR (RT-qPCR) and western blot." (PMID 37427332, 2023). "We next examined whether the effects of RUNX2 on gastric cancer cells were mediated by the overexpression of MMP13 and MGAT5." (PMID 37256183, 2023). "We further found that the effects of RUNX2 are mediated through the activation of MGAT5 and MMP13 both in vitro and in vivo, as their overexpression could compensate for RUNX2 depletion in gastric cancer cell lines and xenograft tumor models." (PMID 37256183, 2023). "Hence, our experiments were conducted to investigate the relationships among RUNX2, MGAT5 and MMP13 in gastric cancer." (PMID 37256183, 2023). "Therefore, the present study aimed to investigate the role of the ISLR gene in gastric cancer and examine whether ISLR could interact with MGAT5 to affect the malignant progression of gastric cancer." (PMID 37427332, 2023).
hepatocellular carcinoma (10 papers, 2007 to 2024). A malignant tumor that arises from hepatocytes. "In hepatocellular carcinoma and non-small cell lung cancers, for example, low expression levels of β1,6-branched N-glycans and Mgat5 are associated with poor prognosis, suggesting tissue-specific effects." (PMID 26760037, 2016). "In hepatocellular carcinoma cells, HGF-induced EMT was associated with decreased expression of MGAT3 and increased MGAT5 expression." (PMID 34356834, 2021). "Notably, BARX1 expression is decreased in hepatocellular carcinoma (HCC), and its absence causes enhancement of tumour invasion and metastasis by inducing MGAT5 and MMP9 expression." (PMID 36927457, 2023). "In addition, m6A methylation can also improve the stemness of hepatoma cells by regulating the stability of MGAT5 mRNA." (PMID 35530319, 2022). "In hepatocellular carcinoma cells, EMT induced by HGF reduced the expression of MGAT3 but increased that of MGAT5, FUT8 and B3GALT5." (PMID 34356834, 2021).
autoimmune disease (8 papers, 2011 to 2025). A disorder resulting from loss of function or tissue destruction of an organ or multiple organs, arising from humoral or cellular immune responses of the individual to their own tissue constituents. "MGAT5-deficient mice exhibit complex phenotypes, including susceptibility to autoimmune diseases and reduced cancer progression." (PMID 40362136, 2025). "β1,6-GlcNAc–branched N-glycans and MGAT5 also present an essential role in regulation of the immune system, since it has been widely reported that mice deficient in MGAT5, and therefore β1,6-GlcNAc–branched N-glycans, are highly susceptible to autoimmune diseases." (PMID 36827215, 2023). "MGAT5 enzyme deficiency reduces the threshold required for the activation of T cells, thus increases the risk of losing immune tolerance and promotes susceptibility to autoimmune diseases such as psoriasis." (PMID 31130981, 2019). "Further studies are required to pinpoint the direct involvement of MGAT5 and NKG2DLs in cancer and autoimmune diseases." (PMID 32849657, 2020). "In the context of inflammatory and autoimmune diseases, the pro-inflammatory cytokine milieu can promote significant changes in cellular glycosylation, including downregulation of N-acetylglucosaminyltransferase V (MGAT5) expression." (PMID 37582971, 2023). "Mice deficient in Mgat5 developed autoimmune disease due to dampened negative regulation of T cell activities." (PMID 36217547, 2022).
colon cancer (8 papers, 2007 to 2023). "Another gene involved in TGF-β signaling, MGAT5, has been linked to tumor growth and invasion, as well as maintenance of colon cancer stem cells." (PMID 33413550, 2021). "When the mRNA levels for MGAT5 were compared between cancer groups with a lower Astler-Coller grade (A-B2) and a higher grade (C1-D), elevated MGAT5 expressions were observed in colon cancer tissues of late stages compared to those of early stages." (PMID 28178684, 2017). "Recently, it was also showed that overexpression of MGAT5 in CRC cells increases the size of population representative of colon cancer stem cells (CSC)." (PMID 26539643, 2016). "Besides involvements in a variety of stages during cancer progression, MGAT5 has been reported to confer anoikis resistance in liver and colon cancer." (PMID 28178684, 2017). "Herein, we report how MGAT5 confers resistance to anoikis stress in colon cancer cells." (PMID 28178684, 2017). "Taken together, these data suggest that MGAT5 reinforces anoikis resistance of colon cancer cells." (PMID 28178684, 2017). "Further, matching the IGF2BP1 interactome data with transcriptomic data, we have found 17 common genes, including MGAT5 and MET, which showed a higher degree of expression in colon tumors analyzed from the TCGA database." (PMID 37829185, 2023). "MGAT5 stimulated MT1-MMP expression in cancer cells and the elevated MT1-MMP expression enhanced the proteolytic capacity in colon cancer cells, thereby reinforcing their invasive and metastatic potential." (PMID 28178684, 2017).
melanoma (8 papers, 2008 to 2025). A malignant, usually aggressive tumor composed of atypical, neoplastic melanocytes. "Expression of MGAT5/GnT-V is transcriptionally regulated by several oncogenic inputs, including the transcription factor Ets-1 in several cancer cell lines including melanoma and by the receptor tyrosine kinases Her-2/neu and Src." (PMID 34440905, 2021). "Among them we found MGAT5, which in melanoma plays a role during the transition from the vertical growth phase to the metastatic stage, together with its targets MCAM, and TGFβ expressed in most malignant melanomas and correlating with poor survival." (PMID 26912358, 2016). "Interestingly, some other factors, as the MGAT5, MCAM and TGFβ1, cooperating in the induction of prometastatic phenotypes in melanoma, were induced by miR-222." (PMID 26912358, 2016).